SP1 (Sp1 transcription factor)
Diseases named in the same sentence as SP1 in open-access papers (continued):
Sharing a sentence is not in itself a finding about the gene and the disease.
glioblastoma (48 papers, 2013 to 2025). The most malignant astrocytic tumor (WHO grade IV). "Interestingly, TLR-4, a protein belonging to the family of toll-like receptors that participate in the inflammatory response and the transcription factor Sp1, have been linked to the progression of glioblastoma multiforme (GBM)." (PMID 36520928, 2022). "In addition, has been suggested that increased activation of HDAC1/2/6 and Sp1 underlies therapeutic resistance and tumor growth in glioblastoma." (PMID 35545840, 2022). "A recent study in glioblastoma demonstrated that the HDAC1/2/6/SP1 pathway promoted therapeutic resistance by upregulating DNA repair pathways." (PMID 39800760, 2025). "It was also revealed that downregulation of SP1 sensitizes human glioblastoma and leukemic cells to radiation-induced DNA double-strand breaks." (PMID 39800760, 2025). "Sp1 is overexpressed in glioblastoma cells and plays a role in maintaining stemness and drug resistance in this tumor type." (PMID 36982239, 2023). "Subsequently, GDF15 activated the transcriptional promoter VEGFA in the human glioblastoma cell line U373 through p-MAPK1/SP1 signaling." (PMID 35280749, 2022). "An in silico study of the regulatory regions of genes differentially expressed by MEOX2 knock-down revealed that they mainly consisted of GC-rich regions enriched for Sp1 and Klf4 binding motifs, two main regulators of metabolism in glioblastoma." (PMID 35565433, 2022). "Either Sp1 or TIMP1 was highly expressed in glioblastoma patients and correlated with poor prognosis." (PMID 35778451, 2022). "Sp1 and Klf4, both main regulators of metabolism in glioblastoma, were the highest-ranking transcription factors whose motifs were enriched in all DEGs, but in particular in the shared downregulated genes." (PMID 35565433, 2022). "For instance, miR-130a-3p expression decreased in glioblastoma cell lines, and the target regulates the expression of Sp1." (PMID 35198024, 2022). "Several of these TFs, including GATA1 and SP1, have been suggested to be involved in the progression and invasiveness of glioblastoma cells." (PMID 32974985, 2020). "In glioblastoma cells, miR-377 targets specific protein 1 (Sp1), resulting in the inhibition of tumor cell proliferation and invasion." (PMID 31757094, 2019). "miR-377 suppresses human glioblastoma proliferation and invasion by targeted-regulation of specific protein 1 (Sp1)." (PMID 30305135, 2018). "This idea is consistent with the report showing that SP1 is required for the EGF-induced expression of Arf6 mRNA in the human glioblastoma cell line U87 cells." (PMID 28429746, 2017). "Similarly, the synthetic analog EF24 shows potent telomerase inhibition in glioblastoma xenografts by suppressing Sp1-mediated hTERT transcription." (PMID 41301813, 2025). "Notably, overexpression of SP1 was also observed in other malignant tumors, such as glioblastoma and stomach adenocarcinoma." (PMID 40832790, 2025). "In addition, it has been suggested that increased activation of HDAC1/2/6 and Sp1 is the basis of glioblastoma drug resistance and tumor growth." (PMID 36227941, 2022). "Additionally, miR-376a was found to inhibit the growth of glioblastoma multiforme via targetting SP1." (PMID 29654167, 2018). "It has been suggested that MGMT expression may be regulated by inhibiting its upstream TF, such as SP1 in glioblastoma." (PMID 25514975, 2015). "SP1 was also identified as a candidate TF and the majority of its downstream targets were differentially expressed in glioblastoma, thus indicating that SP1 may be critical for the development of glioblastoma." (PMID 25514975, 2015). "Furthermore, we discovered that ATM expression and activation under severe hypoxia are regulated through the energy sensor AMPK and the stress-responsive transcription factor Sp1, contributing to cellular radioresistance in a glioblastoma multiforme (GBM) cell line T98G." (PMID 40244269, 2025).
glioblastoma (continued). "Sp1 is involved in the recurrence of glioblastoma (GBM) due to the acquirement of resistance to temozolomide (TMZ)." (PMID 35337344, 2022). "This has been demonstrated in non-small cell lung cancer and glioblastoma cells, where HDAC inhibition increases SP1 acetylation, reduces its binding to target promoters, and suppresses downstream gene expression." (PMID 40885718, 2025). "Another mechanism by which BK regulates migration in glioblastoma cells is the activation of STAT3 and the promotion of its interaction with SP-1." (PMID 39519260, 2024). "Based on these findings, in the present report, we evaluated the contribution of α2δ-1 to the proliferation and migration processes of U87 human glioblastoma cells and its possible regulation through the activation of TLR-4 and Sp1 signaling pathway." (PMID 36520928, 2022). "In temozolomide-sensitive glioblastoma cell, the CGI hypermethylation of SNHG12 promoter blocked the occupancy of SP1 and inhibited the expression level of SNHG12." (PMID 34175894, 2021). "Previous studies have targeted the transcriptional activity of SP1 to regulate the expression of MGMT and other genes for glioblastoma therapy." (PMID 25514975, 2015). "Hence, Sp1 phosphorylation and deacetylation are central to DHEA-mediated DNA repair inducing TMZ resistance in glioblastoma." (PMID 39228402, 2024). "Sp1‐regulated PGE2 production activates fatty acid oxidation (FAO) and the tricarboxylic acid cycle (TCA cycle) in mitochondria through EP1 and EP3 receptors, resulting in temozolomide (TMZ) resistance in glioblastoma multiforme (GBM)." (PMID 37746665, 2023). "Previous studies in human tumors have shown that Sp1 and TLR-4 participate in glioblastoma development; therefore, the overexpression of these proteins was subsequently evaluated separately in U87 glioblastoma cells to assess their role in cell proliferation and migration." (PMID 36520928, 2022). "Moreover, the transcriptional activity of the VEGF promoter in glioblastoma cells can be synergistically activated by STAT3 and Sp1 (Loeffler, Fayard, Weis, & Weissenberger, 2005)." (PMID 32144747, 2020). "A study found that by enhancing FAO and TCA cycles, Sp1-mediated PGE2 up-regulation increased mitochondrial ATP production, leading to glioblastoma (GBM) cell resistance to temozolomide." (PMID 40514365, 2025). "In glioblastoma cell lines under hypoxia, HIF-1α can stimulate the expression of H19 by directly binding to the H19 promoter, or by up-regulating the expression of specific protein 1 (SP1) protein and then binding to the H19 promoter to promote the expression of H19." (PMID 36139386, 2022). "Therefore, we also investigated that Sp1 involved Bcl-w-induced invasion signaling in glioblastoma cells (data not shown; in submission)." (PMID 23826359, 2013).
melanoma (43 papers, 2009 to 2025). A malignant, usually aggressive tumor composed of atypical, neoplastic melanocytes. "Comparisons across these four datasets showed high expression of either RelA (consensus HR = 1.47), POLE4 (consensus HR = 1.39) or SP1 (consensus HR = 1.48) was consistently associated with an increased risk of death in melanoma." (PMID 27203220, 2016). "In addition, we analyzed the enrichment of transcription regulators with the 66 significant enhancers and found that several critical melanoma-associated TFs (e.g., SP1, SNAI2, HEXIM1, ASCL1) preferentially bind at these enhancer loci." (PMID 37904237, 2023). "Accordingly, we found that Sp1 was significantly enriched in the SPARC promoter region (−175 to −25 nt relative to the TIS) in melanoma cell lines as determined by chromatin immunoprecipitation, but not in the IgG controls." (PMID 40943659, 2025). "Overall, Sp1 motifs were enriched at PRRX1-binding sites in WM 793-expressing cells, suggesting a cooperative role between PRRX1 and Sp1 in the transcriptional activation of the SPARC gene in melanoma cells." (PMID 40943659, 2025). "Together, our work suggests that PRRX1 expression, β-catenin/TCFL2, c-Jun, and Sp1 converge to achieve maximal SPARC promoter activity in melanoma cells." (PMID 40943659, 2025). "Both MAPK and JNK transduction pathways are activated in melanoma cells and can phosphorylate Sp1, which in turn leads to basal or activated transcription." (PMID 40943659, 2025). "Inhibition of Sp1 with decoy oligodeoxynucleotides was shown to decrease in vivo expression of Tnf in B16-F10 melanoma cells." (PMID 37043573, 2023). "The melanoma tumor suppressor gene HEXIM1 is upregulated by obligatory binding of SP1 under nucleotide stress conditions." (PMID 37904237, 2023). "In melanoma, aberrant HGF/Met signaling can promote melanoma metastasis by enhancing Ezrin expression via the Sp1 transcription factor." (PMID 37371090, 2023). "In another study, a functional polypeptide JP1 was demonstrated to activate p-MEK1/2 and induced SP1 ubiquitination through the NEDD4L-SP1-Integrin αvβ3 pathway, which inhibited melanoma cell proliferation and metastases." (PMID 36293239, 2022). "Due to the heterogeneity of different tumors, JWA mainly inhibits the formation of blood vessels in melanoma by down-regulating the integrin-linked kinase (ILK) signaling pathway through suppressing intergrin αvβ3 and transcription factor SP1 expression." (PMID 36230577, 2022). "In conclusion, our study demonstrated that the insect-derived peptide PCC-1 induces cell proliferation inhibition, apoptosis, and cell cycle arrest by downregulating Sp1 expression in the melanoma cell lines SK-MEL-28 and G361." (PMID 34531430, 2021). "Inhibiting the expression level of Sp1 can significantly inhibit the proliferation of human malignant melanoma cells." (PMID 33767987, 2021). "CD81 membrane protein promotes melanoma cell motility by inducing metalloprotease MT1-MMP expression through the Akt-dependent Sp1 activation signaling pathway." (PMID 34824296, 2021). "Meanwhile, the role of JWA gene on melanoma is SP1 ubiquitination mediated down-regulation of integrin αvβ3." (PMID 32724456, 2020). "JP1 activated expressions of p-MEK1/2 while inhibited SP1 and integrin αvβ3 dose-dependently in human A375 melanoma cells." (PMID 32724456, 2020). "Mechanistically, JP1 was shown to activate p-MEK1/2 and triggered SP1 ubiquitination in melanoma cells." (PMID 32724456, 2020).
melanoma (continued). "We have recently reported that hYSK1 promotes migration of melanoma and fibrosarcoma cells by repressing p16INK4a nuclear translocation via direct interaction, thereby resulting in increased SP-1-mediated MMP2 transcription." (PMID 30646538, 2019). "Upon tetraspanin CD81 stimulation, MMP14 expression as well as MMP14-dependent melanoma invasion and metastasis are increased through Akt-dependent Sp1 activation, which also support the function of Sp1 in regulating the transcription of MMP14." (PMID 31466240, 2019). "Whereas an opposite relationship was observed between the high PAR1 levels in aggressive melanoma and the activator protein-2 (AP-2), a direct correlation is seen with the expression of specificity protein 1 (Sp1)." (PMID 30400241, 2018). "Sp1 influences invasiveness of melanoma cells by regulating cathepsin B and metalloproteinase MT1-MMP expression." (PMID 26885752, 2016). "Most notably, we report that high expression of specific protein 1 (SP1) and polymerase (DNA-directed), epsilon 4, accessory subunit (POLE4) was associated with significantly worse overall survival in the TCGA melanoma cohort." (PMID 27203220, 2016). "Further, aberrant expression of some of these genes including RelA, POLE4 and SP1 had prognostic implications in terms of melanoma patient survival." (PMID 27203220, 2016). "Mutations in melanoma were clustered within ETS and Sp1 transcription factor binding motifs, had a UV signature and were identified in other cutaneous malignancies." (PMID 27611953, 2016). "In a HMGB1 knockdown in melanoma, a marked decrease in cell proliferation was observed mediated by p21 in a SP1 dependent manner." (PMID 26405815, 2015). "NEDD4L ubiquitinates SP1, leading to its degradation, which inhibits melanoma cell proliferation." (PMID 38027016, 2023). "Therefore, we pursued a mechanism of TNF expression in melanoma based on Sp1, Ets-1, and cJUN activity." (PMID 37043573, 2023). "It was also reported that HGF/Met signaling activates the transcriptional factor specificity protein 1 (Sp1) through the MAPK pathway, and that activated Sp1 can in turn directly bind to the promotor of the ezrin gene and regulate its transcription in melanomas." (PMID 35328667, 2022). "Additionally, we discovered a novel anticancer mechanism of insect-derived peptides in melanoma through the regulation of transcription factor Sp1 protein, which is overexpressed in cancer, apoptosis, and cell cycle-related proteins." (PMID 34531430, 2021). "Moreover, CD81 increases melanoma cell motility by up-regulating metalloproteinase expression through Akt-dependent Sp1 activation signaling pathway." (PMID 34824296, 2021). "The hYSK1-mediated loss or downregulation of p16INK4a has been shown to result in an increase in the expression of MMP-2 through transcriptional activation of SP-1, and in the enhancement of the migration and invasion of tumor cells including those of the melanoma and fibrosarcoma." (PMID 30646538, 2019). "Indeed, co-immunoprecipitation experiments in several melanoma lines showed that Sp1 physically binds to SOX9." (PMID 26885752, 2016). "In our study, we found that ING4 significantly reduced the mRNA and protein expressions of MMP-2 and COX-2, which was consistent with the findings in melanoma, osteosarcoma and brain cancer, and the expression of nuclear Sp1 and subsequent DNA binding activity." (PMID 27806345, 2016). "Previous studies have exhibited a functional role for Sp1 in melanoma cells." (PMID 26885752, 2016). "Notably, our data indicates that in melanoma cells Sp1 is involved in deactivation of the CEACAM1 promoter." (PMID 26885752, 2016). "Sialidase NEU3 and GD3 synthase genes were significantly up-regulated in melanomas in comparison to melanocytes, possibly as a direct consequence of the increase expression of the transcriptional factor Sp1, but we cannot record any significant correlation with patients’ survival." (PMID 25085576, 2014).
melanoma (continued). "Thus, in melanoma, the low levels of AP-2α enable SP-1 to bind to its motif in the PAR-1 promoter, which results in PAR-1 gene activation." (PMID 21378407, 2011). "Thus, a specific role for BRG1 in the activation of MMP2 and melanoma invasiveness may result from selective interactions with the SP1 transcriptional regulator." (PMID 20969766, 2010). "SP1 is identified as a substrate of NEDD4L, and NEDD4L downregulates it via ubiquitination at K685 site, inhibiting the proliferation and metastasis of melanoma mediated by the SP1-integrin αvβ3 pathway." (PMID 38027016, 2023). "Consistent with our result, SP1 and HEXIM1 have been documented to play an important regulatory role in inhibiting melanoma-specific gene transcription." (PMID 37904237, 2023). "Several studies have shown that plicamycin can effectively target the activity of SP-1 protein on the SETDB1 promoter to inhibit SETDB1 expression, thus offering a beneficial therapeutic strategy for melanoma." (PMID 36699463, 2022). "In melanoma, NEDD4L is activated by p-MEK1/2 and ubiquitinates SP1 at the K685 residue, which leads to proteasomal degradation of SP1." (PMID 34743202, 2021). "JP1 inhibited expressions of integrin αvβ3 and SP1 in both A375 and MEWO melanoma cells compared to the cells treated by Ctrl-R or PBS." (PMID 32724456, 2020). "In human melanoma cells, AP-2 has been shown to repress PAR-1 expression and compete with the positive regulator Sp1." (PMID 27566553, 2016). "Decline in ARSB leads to reduced binding of galectin-3 with C4S and increased availability of galectin-3 for nuclear translocation and cooperation with AP-1 and Sp1 in promoter activation, for expression of genes such as Wnt9A in colonic epithelium, versican in prostate cells, and CSPG4 in melanoma." (PMID 36361933, 2022). "Upregulation of miR-378a-5p in M14 melanoma cells reduced both mRNA and protein levels of STAMBP, SP1, KLF9, FUS-1, and SUFU when compared with control transfected cells, while miR-378a-5p inhibition led to an opposite effect, upregulating the expression of target genes." (PMID 32060259, 2020). "Co-immunoprecipitation studies show that SOX9 and Sp1 physically interact in melanoma cells, while silencing of SOX9 down-regulates ETS1, but not Sp1, in the same cells." (PMID 26885752, 2016). "Together, our findings suggest that SP1 and POLE4 could represent additional functional targets of miR-7-5p in melanoma, emphasizing the coordinate manner in which miRNAs suppress expression of multiple target genes to exert their biological effects." (PMID 27203220, 2016). "PMA stimulation increased the intensity of one complex band after incubation of nuclear extracts of melanoma or HeLa cells with the CRE probe but did not modify the pattern of protein binding to the Sp1 site." (PMID 27973546, 2016). "Incubation of nuclear extracts of HT1080 cells, HeLa cells, HUVEC or Bowes melanoma cells with a double-stranded IRD700 labeled probe for the GC-rich sequence at +62 to +69, which contains an Sp1-binding site (henceforth named Sp1 probe) produced at least five shifted bands." (PMID 27973546, 2016). "In melanoma, the PAR-1 gene is differentially regulated by activator protein-2α that binds to the PAR-1 promoter in low- and nonmetastatic melanoma cell lines, and SP-1 transcription factors that are active in metastatic melanoma cell lines." (PMID 26573921, 2015). "Consistent with a nuclear function of HMGB1, we demonstrated that HMGB1 regulated cell proliferation via interacting with Sp1 and interfering Sp1-mediated transcription of p21 Together, our study reveals a novel oncogenic role of HMGB1 in promoting human melanoma cell proliferation." (PMID 25051367, 2014). "Both Sp1 and HMGI/Y are expressed in CD133+ melanoma cell lines." (PMID 24194746, 2013).
melanoma (continued). "JP1 was targeted to and entered melanoma cells with high expression of integrin αvβ3 by RGD, and then interacted with MEK1/2 to activate E3 ubiquitination enzyme NEDD4L, which accelerated the degradation of SP1 and ultimately played a transcriptional inhibitory role on integrin αvβ3." (PMID 32724456, 2020). "In addition, another study showed that transcriptional regulators Sp1 (Specificity Protein 1), CREB (CAMP Responsive Element Binding Protein), and p300 (E1A Binding Protein P300) can bind and positively regulate RKIP expression in A375 melanoma and HeLa cells." (PMID 30181452, 2018). "Co-incubation of nuclear extracts and the Sp1 probe with antibodies against Sp1 resulted in the formation of a clear supershifted band with nuclear extracts from HT1080 cells, HUVEC and Bowes melanoma cells but not from HeLa cells." (PMID 27973546, 2016).